CFAP298-TCP10L (CFAP298-TCP10L readthrough)
Synonyms: FLJ10932; C21orf59-TCP10L; C21orf77; LINC00846
Gene: Protein-coding gene on chromosome 21 (32,402,511 to 32,612,865, reverse strand). Ensembl gene ENSG00000265590.
Genetic constraint (gnomAD): Loss-of-function variants: 33 observed, 42.76 expected, observed/expected ratio (o/e) 0.77, 90% interval 0.58 to 1.03. The upper end of that interval is the gene's LOEUF score, 1.03, which puts it in group 4 of 6, group 1 being the genes least tolerant of losing a copy. Missense variants: 437 observed, 473.97 expected, observed/expected ratio (o/e) 0.92, 90% interval 0.85 to 1. Synonymous variants: 181 observed, 181.5 expected, observed/expected ratio (o/e) 1, 90% interval 0.88 to 1.13.